CRP (C-reactive protein)
Diseases named in the same sentence as CRP in open-access papers (continued):
Sharing a sentence is not in itself a finding about the gene and the disease.
insomnia (95 papers, 2013 to 2026). A sleep disorder characterized by difficulty in falling asleep and/or remaining asleep. "MRS-CRP stands out as the only CRP measure associated with insomnia and OSA severity markers including REI, minimum and mean SpO2." (PMID 40437222, 2025). "The study reported that short sleep duration and insomnia symptoms were associated with increases in inflammatory cytokines such as CRP and IL6." (PMID 36849922, 2023). "Insomnia symptoms have been reported to be significantly associated with higher levels of CRP in a cohort of Swedish women." (PMID 36579654, 2023). "Insomnia is linked to elevated CRP and high BMI has been associated with more tender points and greater fatigue and tiredness in FM patients." (PMID 35832286, 2022). "The scenario changes radically in pathophysiological conditions such as insomnia, a prevalent sleeping disorder in older adults associated with pro-inflammatory markers IL-6 and C-reactive protein." (PMID 36183306, 2022). "Previous studies have reported associations of insomnia and sleep disturbances with elevated levels of inflammatory biomarkers, including several biomarkers considered in our analyses such as CRP, IL-6 and TNF-α." (PMID 36104003, 2022). "This is consistent with other research, in which insomnia symptoms were associated with higher CRP levels in young adults (21–35 years old)." (PMID 36140260, 2022). "Insomnia is, in fact, associated with marked decreases in the numbers of T-cells and high levels of CRP and of both IL-6 and TNF." (PMID 35444704, 2021). "Results indicated that sleep disturbance was associated with higher levels of IL-6 and CRP and that short sleep duration, a common consequence of insomnia, was associated with higher levels of CRP." (PMID 36776493, 2020). "The association between headache and insomnia is well-established, but the impact of insomnia on the relationship between hs-CRP and migraine is unclear." (PMID 31558164, 2019). "The coexistence of arthralgia, fatigue, and insomnia is associated with elevated C-reactive protein and other inflammatory biomarkers." (PMID 29890985, 2018). "In an exploratory analysis of fatigue and insomnia, all of these biomarkers also showed an association with fatigue and insomnia, with the exception of a trend toward significance for CRP and insomnia." (PMID 26126656, 2015). "Among women taking AIs, the coexistence of arthralgia, fatigue, and insomnia was associated with increased levels of inflammatory biomarkers (elevated CRP, eotaxin, MCP-1, and VDBP)." (PMID 26126656, 2015). "Previous epidemiologic studies, based on questions about sleep duration or insomnia and findings such as an increase in CRP, have suggested a causative relationship between cardiometabolic diseases and insufficient sleep." (PMID 24194869, 2013). "Furthermore, a positive association between insomnia and C-reactive protein levels has previously been shown in standard observational research." (PMID 37013595, 2023). "We interpreted the MR results as reflecting a lifetime susceptibility to insomnia on the basis that SNPs are determined at conception, and evidence suggested that with similar analyses of other exposures (e.g., blood pressure and C-reactive protein) this is the case." (PMID 36067251, 2022). "Disturbed sleep and insomnia are also strongly associated with upregulation of CRP and IL-6." (PMID 33994998, 2021). "Remission of insomnia was also associated with lower levels of CRP at 16 months." (PMID 36776493, 2020). "Changes in IP-10 and TNF-RII levels were associated with worsening of general fatigue (P = 0.03 and P = .02, respectively), and statistically significant associations were observed between insomnia and CRP, IFN-r, IFN-α2a, IL-17A, IP-10, and TNF-RII (P < .05 for all)." (PMID 33134822, 2020). "We evaluated insomnia as a modifying factor on the association between hs-CRP and headache." (PMID 31558164, 2019).
insomnia (continued). "Furthermore, insomnia symptoms in combination with objectively-verified sleep duration of <7 h were associated with higher CRP levels as early as adolescence (n = 378)." (PMID 30920354, 2019). "The aim of this large-scale population-based study was to evaluate the cross-sectional association between hs-CRP and types of headache, and to see whether the relationship to insomnia could be reproduced." (PMID 31558164, 2019). "In one of the largest CBT-I studies with over 100 older adults suffering from primary insomnia, CBT-I resulted in lower levels of CRP throughout the 16-mo follow-up period compared with adults receiving sleep education, and this decrease was associated with remission of insomnia." (PMID 30920354, 2019). "After adjusting for relevant covariates, both insomnia (OR = 1.806, 95% CI = 1.037–3.146, p < 0.05) and CRP (OR = 1.384, 95% CI = 1.026–1.867, p < 0.05) emerged as independent factors significantly associated with TCFA." (PMID 41328712, 2025). "Patients with insomnia and shortened sleep duration exhibit elevated systemic C-reactive protein (CRP) levels, correlating with chronic inflammatory states." (PMID 40171499, 2025). "Logistic regression identified both insomnia (OR = 1.806; p = 0.037) and CRP (OR = 1.384; p = 0.034) as independent predictors of TCFA." (PMID 41328712, 2025). "Beyond insomnia itself, elevated CRP levels also emerged as an independent predictor of TCFA in our analysis." (PMID 41328712, 2025). "We also found evidence that chronic pain was positively causally associated with SUDs (alcohol, cannabis, opioids, and tobacco), ADHD, insomnia, and CRP level." (PMID 40297705, 2025). "Baseline characteristics were reanalyzed according to TCFA presence, revealing statistically significant differences in insomnia, CRP, TC, and LDL‐C levels between the two groups." (PMID 41328712, 2025). "Laboratory examination showed that the level of CRP in insomnia group was significantly higher than non‐insomnia group [2.89 (2.22,3.39) vs. 2.42 (1.81,3.19), p < 0.05]." (PMID 41328712, 2025). "The present study also found that the leukocyte count, neutrophil count, and serum CRP levels in the peripheral blood of the insomnia group in the acute phase were higher than those in the non-insomnia group." (PMID 37924679, 2023). "Regarding CRP, there was a significant association between insomnia severity (ISI) and CRP score change from T2-T1, indicating that patients with worse insomnia showed higher CRP levels." (PMID 37081449, 2023). "Secondary outcomes will be changes in psychiatric disorders, rumination, worry, type D-personality, metacognitions, insomnia, quality of life, and C-Reactive protein (CRP)." (PMID 37790218, 2023). "Nevertheless, we found a significant association between greater sleep fragmentation and IL-6, decreased SWS and TNF-α, and greater insomnia severity, sleep duration, and CRP." (PMID 37081449, 2023). "A meta-analysis assessing more than 50,000 patients revealed a significant increase of CRP and IL-6 levels in subjects suffering from sleep disturbances (confirmed by questionnaires, interviews, or insomnia diagnosis)." (PMID 36140260, 2022). "C-reactive protein levels showed small genetic correlations with MD and insomnia (eTable 10 in the Supplement)." (PMID 33079133, 2021). "Similar adjustments were performed for insomnia, and the association between insomnia and IP-10 and TNF-RII, as well as CRP, IFN-r, IFN-α2a, and IL-17A also remained statistically significant (P < .05 for all)." (PMID 33134822, 2020). "Of all the depressive symptoms measured, so-called vegetative symptoms (psychomotor retardation, insomnia, difficulty getting started, difficulty working) were more important in explaining higher CRP." (PMID 29764522, 2019). "Increased high sensitivity C- reactive protein (hs-CRP) levels have been found in many earlier studies on migraine, and recently also in persons with migraine and insomnia." (PMID 31558164, 2019).
insomnia (continued). "In patients with insomnia, elevated levels of C-Reactive Protein were found, which are also present during inflammation." (PMID 26448877, 2015). "Insomnia severity also correlates positively with log-transformed CRP (log-CRP) levels." (PMID 41048872, 2025). "Nevertheless, they suggest that the HRV–insomnia association observed here is unlikely to be mediated solely through CRP- or IL-6–related systemic inflammation." (PMID 41492523, 2025). "Similarly, individuals with insomnia exhibit elevated levels of CRP, along with other pro-inflammatory cytokines (e.g., IL-6 and TNF-α)." (PMID 41048872, 2025). "This relationship remained statistically significant and changed little when additionally controlling for sleep duration, sleep quality, insomnia symptoms, use of sleep medications, use of nervous medications, glucose, insulin, lipids, dietary energy intake, and C-reactive protein." (PMID 38956441, 2024). "Importantly, however, we argue that the effect of IL6 trans signaling interpretation can be problematic, since our multivariable MR clearly showed that the effect of sIL6R on insomnia is confounded or mediated by CRP." (PMID 38511149, 2024). "C-reactive protein is a marker of inflammation which is itself a response of the immune system, providing evidence that insomnia may affect the immune system." (PMID 37013595, 2023). "A biological plausible reduction of CRP during the five-month follow-up could be due to better sleep quality since the workers reported fewer symptoms of insomnia during plant shutdown." (PMID 35735819, 2022). "In another study on insomnia, symptoms with objective short sleep duration (<7 h) were associated with elevated levels of CRP in adolescents compared to the other groups, including those with objective short sleep duration without insomnia symptoms." (PMID 36140260, 2022). "Interestingly, this association remained independent and significant when neuroticism and depression were included in the model, which highly implies that objective short sleep duration with insomnia symptoms directly correlates with CRP elevation." (PMID 36140260, 2022). "In one of the largest randomized controlled trials evaluating the impact of CBT-I on insomnia and inflammation, results indicated that CBT-I was associated with a reduced risk of high CRP levels (>3.0 mg/L) at 16 months as compared to both tai chi and a sleep education control." (PMID 36776493, 2020). "Another justification for the significant relationship of shift work with high serum hs-CRP level may be the higher rate of sleep problems (such as insomnia and sleep inadequacy) among our shift worker participants." (PMID 31814938, 2019). "Despite the special relationship between chronic inflammation and OSA, plasma CRP levels have never been studied as a risk factor for OSA in the general population or insomnia sufferers." (PMID 28683800, 2017). "Moreover, in an observational study of military personnel with insomnia, CRP level was reduced more in the restorative sleep group than in those with persistent insomnia." (PMID 26435495, 2015). "This is in line with a previous large scale cross sectional study of n = 8547 adults from Norway, which also found no consistent associations between symptoms of insomnia and CRP." (PMID 25093413, 2014). "The Hunt study of 8547 men and non-pregnant women also did not support a significant association between insomnia and CRP." (PMID 24663098, 2014). "In addition, other psychosocial and behavioral phenomena related to stress (including hostility, insomnia, and childhood adversity) have been associated with CRP but not cytokines." (PMID 35087386, 2021). "Assessing different inflammatory markers, such as C-reactive protein (CRP) and cortisol hormone, would give depth to the study, in which they are correlated with total scores of GAD and insomnia and the proportion of peripheral immune subsets." (PMID 41451218, 2025).
insomnia (continued). "Previous studies have demonstrated that insomnia patients exhibit elevated levels of IL-6, IL-10, IL-1β, TNF-α, CRP, and other inflammatory markers." (PMID 40636389, 2025). "Conversely, outcomes such as waist circumference, CRP, IL-6, TNF-α, QoL (quality of life), fatigue, pain, insomnia, physical functioning, and emotional functioning were rated as moderate quality due to small sample sizes." (PMID 40642165, 2025). "In the usually insomnia group, the edge weights between “PHQ9–4-GAD7–2 (Energy–Uncontrollable worry)”, “PHQ9–4-GAD7–4 (Energy–Trouble relaxing)”, “PHQ9–4-CRP (Energy–CRP)”, and “PHQ9–5-CRP (Appetite–CRP)” were significantly higher than in the group that never/rarely experienced insomnia." (PMID 41048872, 2025). "Inflammation markers such as CRP,TNF-α, and IL-6 may represent a common physiological process linkingshorter sleep duration and insomnia to mortality." (PMID 39867194, 2025). "Cognitive behavioral therapy for insomnia (CBT-I) has been found to be highly effective in a primary care setting, and there is also suggestive evidence that such treatment can reduce the level of CRP in the blood." (PMID 36937728, 2023). "Adolescents are not spared: compared to controls, those suffering from insomnia and short sleep duration exhibit systemic inflammation and significantly higher CRP level." (PMID 33994998, 2021). "Insomnia, recruitment year, and MDD all show significant but marginally important effects on CRP." (PMID 34733313, 2021). "Whereas the volunteers who slept >8 h/day with or without insomnia symptoms had significantly increased odds ratios of high systolic blood pressure and high triglycerides in model 1, as well as high CRP in model 2 (p < 0.05)." (PMID 31404954, 2019). "No clear relationship was found between elevated hs-CRP and headache less than 7 days/month or with insomnia." (PMID 31558164, 2019). "NCTs revealed significant differences in global strength (S = 0.178, p < 0.01) and edge weights (M = 0.062, p < 0.01) between the never/rarely and usually insomnia groups, with stronger connections between depressive symptoms (energy/appetite) and CRP in the usually insomnia group (p < 0.001)." (PMID 41048872, 2025). "The coexistence of arthralgia, fatigue and insomnia after adjusting for race, chemotherapy history, nonsteroidal antiinflammatory drugs (NSAIDs), age and BMI was in connection with elevated C-reactive protein (CRP), eotaxin, monocyte chemokine-1 as well as vitamin D-binding protein (VDBP)." (PMID 36578931, 2022).
chorioamnionitis (94 papers, 2007 to 2026). A morphologic finding indicating inflammation of the fetal sac membranes. "In their study, they demonstrated that the diagnostic accuracy of CRP in the detection of chorioamnionitis is significantly improved when pregnancy-appropriate reference intervals are used compared to the current guidelines’ cut-off values." (PMID 40002566, 2025). "The results of their analyses also clearly show that histopathological chorioamnionitis is associated with a higher concentration of C-reactive protein in the newborn and a lower gestational age." (PMID 41470233, 2025). "The increase in CRP was specifically associated with the presence of funisitis in addition to histopathologic chorioamnionitis (p < 0.01)." (PMID 37606448, 2023). "As a result, CRP can be used as a screening diagnostic for chorioamnionitis since it is an indirect biomarker of IL-6 secretion." (PMID 37919654, 2023). "Maternal plasma IL-6 independently predicts intra-amniotic infection in women with preterm labor; however, it has worse diagnostic performance than that of AF IL-6 and similar performance to that of serum CRP." (PMID 29743041, 2018). "In conclusion, maternal plasma IL-6 independently predicts intra-amniotic infection in women with preterm labor; however, it has worse diagnostic performance than that of AF IL-6 and similar performance to that of serum CRP." (PMID 29743041, 2018). "On multivariate analyses, an elevated plasma IL-6 level was significantly associated with intra-amniotic infection and imminent preterm delivery after adjusting for confounders, including high serum CRP levels and short cervical length." (PMID 29743041, 2018). "The pioneering papers regarding the associations between maternal serum CRP concentration and infectious-related and inflammatory complications, mainly clinical and histological chorioamnionitis, in PPROM have been published in nineties’ of the last century." (PMID 28813455, 2017). "Compared to body temperature, heart rate, WBC count, and CRP level in maternal peripheral blood, DNA amount and especially, 16S rDNA copy number demonstrated higher diagnostic accuracy for both miCAM and chorioamnionitis." (PMID 28939908, 2017). "CRP was the only factor significantly associated with both clinical and histological chorioamnionitis, and it was linearly associated with these outcomes." (PMID 21470433, 2011). "C-reactive protein was associated with clinical and histological chorioamnionitis, with areas under the receiver operating characteristic curve of 0.61 (95% CI [0.48, 0.74]) and 0.62 (95% CI [0.47, 0.74]), respectively." (PMID 21470433, 2011). "A CRP concentration of 5 mg/L or more was also associated with both clinical and histological chorioamnionitis, but its predictive values for both outcomes were low." (PMID 21470433, 2011). "However, maternal chorioamnionitis and elevated maternal C-reactive protein (CRP) were associated with a higher neonatal inflammatory status." (PMID 40295408, 2025). "In addition to that, meconium aspiration syndrome, surgical procedures, chorioamnionitis, and perinatal anoxia can also cause higher serum CRP concentration." (PMID 36834338, 2023). "In the absence of a positive culture, a majority of preterm infants receive antibiotics immediately after birth based on maternal risk factors (e.g. intra-amniotic infection) or laboratory abnormalities [e.g. elevated serum C-reactive protein (CRP)] because of the risk of mortality." (PMID 33479274, 2021). "In the multivariable analysis, elevated VDBP levels in CVF samples of PTL women were significantly associated with intra-amniotic infection and imminent preterm delivery, even after adjusting for potential confounders (e.g., gestational age at sampling, parity, and serum CRP)." (PMID 29879190, 2018).